NSMF (NMDA receptor synaptonuclear signaling and neuronal migration factor)
Description:
Couples NMDA-sensitive glutamate receptor signaling to the nucleus and triggers long-lasting changes in the cytoarchitecture of dendrites and spine synapse processes. Part of the cAMP response element-binding protein (CREB) shut-off signaling pathway. Stimulates outgrowth of olfactory axons and migration of gonadotropin-releasing hormone (GnRH) and luteinizing-hormone-releasing hormone (LHRH) neuronal cells.
Synonyms: NELF; HH9
Tractability: Antibody: UniProt places it where antibodies can reach, with high confidence; its Gene Ontology location is reachable by antibodies, with medium confidence.
Gene: Protein-coding gene on chromosome 9 (137,447,570 to 137,459,576, reverse strand). Ensembl gene ENSG00000165802.
Subcellular location: Nucleus; Nucleus envelope; Nucleus membrane; Nucleus matrix; Cytoplasm; Cytoplasm, cell cortex; Cytoplasm, cytoskeleton; Cell membrane; Cell projection, dendrite; Synapse; Synapse, synaptosome; Postsynaptic density; Membrane
Subcellular location (Human Protein Atlas): Nucleoplasm
Gene Ontology:
Molecular function: calcium-dependent protein binding
Biological process: positive regulation of neuron migration; cellular response to amino acid stimulus; cellular response to electrical stimulus; cellular response to gonadotropin stimulus; regulation of dendrite morphogenesis; regulation of neuron apoptotic process; regulation of neuronal synaptic plasticity; regulation of neuron migration
Cellular component: cytoplasm; nucleoplasm; nucleus; apical dendrite; cortical cytoskeleton; dendrite; euchromatin; membrane; neuron projection; nuclear envelope; nuclear matrix; nuclear membrane; perikaryon; postsynaptic density; synapse; cell cortex; cytoskeleton; plasma membrane
Genetic constraint (gnomAD): Loss-of-function variants: 31 observed, 63.63 expected, observed/expected ratio (o/e) 0.49, 90% interval 0.37 to 0.66. The synonymous counts are far from expectation, so gnomAD's model fits this gene poorly and the ratio says little. Missense variants: 673 observed, 690.94 expected, observed/expected ratio (o/e) 0.97, 90% interval 0.91 to 1.04. Synonymous variants: 345 observed, 268.41 expected, observed/expected ratio (o/e) 1.29, 90% interval 1.18 to 1.4.
Homologues: Orthologues: chimpanzee NSMF (100% identical), macaque NSMF (99% identical), dog NSMF (96% identical), pig NSMF (95% identical), mouse Nsmf (94% identical), rat Nsmf (92% identical), guinea pig NSMF (89% identical), rabbit NSMF (77% identical), tropical clawed frog nsmf (70% identical), zebrafish nsmfa (61% identical), zebrafish nsmfb (60% identical).
Diseases named in the same sentence as NSMF in open-access papers:
NSMF is named in the same sentence as 12 diseases in open-access papers, as found by Europe PMC text mining. Sharing a sentence is not in itself a finding about the gene and the disease. The quoted sentences say what the papers report.
Kallmann syndrome (4 papers, 2012 to 2023). Kallmann syndrome (KS) is a developmental genetic disorder characterized by the association of congenital hypogonadotropic hypogonadism (CHH) due to gonadotropin-releasing hormone (GnRH) deficiency, and anosmia or hyposmia (with hypoplasia or aplasia of the olfactory bulbs). "We recently reported that the N-methyl-D-aspartate receptor synaptonuclear signaling and neuronal migration factor (NSMF), a neuronal protein associated with Kallmann syndrome, promotes RPA32 phosphorylation via ATR upon replication stress." (PMID 37378431, 2023). "Several subsequent publications have tried to establish a link between mutations in the NSMF gene that encodes for Jacob/NELF and Kallmann syndrome (KS)." (PMID 26977770, 2016). "Several reports indicate that mutations in NSMF are related to Kallmann syndrome (KS), a neurodevelopmental disorder characterized by idiopathic hypogonadotropic hypogonadism (IHH) associated with anosmia or hyposmia." (PMID 26977770, 2016). "Mutations in Kallmann Syndrome (KS) genes such as ANOS1 and NSMF, leading to hypogonadotropic hypogonadism with anosmia, have not been found in individuals with self-limited pubertal delay." (PMID 31293522, 2019).
NSMF also shares sentences with these, for which no sentence is quoted: breast carcinoma (2 papers); Anosmia (1); asthma (1); cancer (1); CHARGE syndrome (1); Crohn disease (1); hypogonadism (1); insomnia (1); latent infection (1); neurodevelopmental disorder (1); Noonan syndrome (1).